CD36 (CD36 molecule (CD36 blood group))
Diseases named in the same sentence as CD36 in open-access papers (continued):
Sharing a sentence is not in itself a finding about the gene and the disease.
malaria (continued). "This comparativeanalysis demonstrates the predictability of P. falciparum-IEbinding to the two major cytoadhesion receptors CD36 and ICAM-1 and provides newinsight into how natural selection may be shaping the PfEMP1 binding repertoire toexploit distinct host niches of varying anti-malaria immunity." (PMID 21573138, 2011). "MTRAP proteins from other human malaria parasites were also examined in this BLI experiment and did not bind to CD36, addressing any concern about the weakness of ELISA in detecting weak interactions." (PMID 37981686, 2023). "Studies have also shown that parasites isolated from patients with severe malaria express high levels of group A PfEMP1 that do not bind CD3612,35, suggesting the role of avoiding recognition by CD36 is a mechanism of parasite evasion of macrophage phagocytosis." (PMID 35831417, 2022). "However, the CD36 adhesion phenotype is not a common feature of malaria, as placenta-sequestered parasites are known to more strongly adhere to CSA as opposed to CD36." (PMID 26385579, 2015).
metabolic syndrome (106 papers, 2006 to 2025). A cluster of metabolic risk factors for CARDIOVASCULAR DISEASES and TYPE 2 DIABETES MELLITUS. "For SNP rs1761667, the rare A allele has been associated with a reduced expression of the CD36 transcript having an impact on metabolic syndrome development, HDL metabolism and vitamin E absorption." (PMID 39859364, 2025). "Abnormal upregulation of CD36 can promote inflammation, foam cell formation, and EC apoptosis, but CD36 deficiency can also lead to dyslipidemia and metabolic disorders." (PMID 37123258, 2023). "Handberg then concluded that sCD36 reflects the expression of CD36 in some tissues associated with metabolic syndrome, especially in monocytes and macrophages." (PMID 40625574, 2023). "CD36 deficiency is relatively common in certain populations (3–10%) and CD36 SNPs that reduce CD36 levels result in dyslipidemia and increase the risk of type 2 diabetes." (PMID 36061565, 2022). "In this study, we investigated the potential contribution of CD36 rare mutations to T2D and its cardio-metabolic complications (i.e. hypertension, dyslipidemia and history of coronary heart disease) by screening 184 French cases of European ancestry." (PMID 31748580, 2019). "We showed previously that hypertension in SHR, linked to chromosome 4 in recombinant inbred and congenic strains, is, in part, caused by renal Cd36 deficiency, as a component of the overall metabolic syndrome abnormalities encoded by SHR Cd36." (PMID 28130354, 2017). "CD36 is recognized as a lipid and fatty acid receptor and plays an important role in metabolic syndrome and associated cardiac events." (PMID 24312343, 2013). "CD36 is recognized as a lipid and fatty acid receptor and plays an important role in the metabolic syndrome and associated cardiac events." (PMID 22662181, 2012). "In conclusion, CD36 is generally recognized as an important lipid and FA receptor which plays a role in the metabolic syndrome and its associated cardiac events." (PMID 22662181, 2012). "Our next strategy is to perform the genetic association between CD36 gene SNPs and various metabolic syndrome components." (PMID 23249574, 2012). "From the pilot genotyping results, we found that several CD36 gene SNPs were associated with metabolic syndrome status and metabolic trait, including HDL, triglycerides, body mass index, fasting glucose and triglyceride levels." (PMID 23249574, 2012). "This case–control study assessed the haplotype-tagged SNPs from CD36 on the risk of metabolic syndrome and components." (PMID 23249574, 2012). "Evidence of the genetic association between CD36 candidate gene and the risk of metabolic syndrome and its components has been inconsistent." (PMID 23249574, 2012). "Extensive tagged SNP study on CD36 gene among African-Americans showed this gene was associated with metabolic syndrome and HDL cholesterol." (PMID 23249574, 2012). "A region of chromosome 7 (7q11.2–7q21.11) encompassing the CD36 gene was linked to components of the metabolic syndrome including HDL in genome-wide linkage studies." (PMID 20360851, 2010). "Similarly, forced expression of hepatic CD36 has been linked to significant increases in hepatic fatty acid uptake in vivo, contributing to dyslipidemia." (PMID 39558328, 2024). "SNPs in the apolipoprotein A1 and C3 (APOA1 and APOC3) genes and cluster of differentiation 36 (CD36) gene led to increased risk of metabolic syndrome in subjects with Western dietary pattern and dyslipidemia in individuals who consumed high amounts of fat, respectively." (PMID 37610590, 2023). "It has been found that dyslipidemia enhanced thrombosis can be corrected in CD36 deficiency mice." (PMID 35082966, 2022). "CD36 gene signaling has been implicated in the development of chronic diseases and genetic variants have been associated with lipid abnormalities and susceptibility to metabolic syndrome in humans." (PMID 34630405, 2021).
metabolic syndrome (continued). "However, further studies are still needed to demonstrate the complex interactions between intestinal CD36 and dietary lipids, as well as its importance in diet associated metabolic syndrome." (PMID 33995128, 2021). "Genetic variants in CD36 have been associated with metabolic syndrome." (PMID 34099721, 2021). "Lipid oversupply may induce CD36 sarcolemmal translocation to facilitate fatty acid transport, which in turn causes dyslipidemia and type 2 diabetes." (PMID 31938068, 2020). "In addition, patients with depletion of the CD36 gene are often diagnosed with hyperinsulinism and are prone to metabolic syndrome underlining the importance of FAT/CD36 in the control of metabolism." (PMID 31474875, 2019). "Population studies have also identified several CD36 polymorphisms linked to increased risk of metabolic syndrome, acute myocardial infarction and type 2 diabetes, which might support their determination in the context of personalized therapeutic strategies." (PMID 29883404, 2018). "It has been suggested that CD36 in plasma might represent a marker of the metabolic syndrome, a condition that was found associated with frequent shift work." (PMID 25984797, 2015). "Our data also extend previous findings on the pathogenic role of CD36 in the metabolic syndrome and age-related cardiomyopathy and lipotoxicity in heart and skeletal muscle and suggest that CD36 is also one of the key candidate proteins playing a role in the development of age-related NAFLD." (PMID 24751397, 2014). "Nonetheless, the results of association studies must always be interpreted with caution, especially when multiple comparisons are performed, and replication in other populations is needed before a link between CD36 variants, dyslipidemias and cardiovascular disease." (PMID 24188362, 2013). "However, no special ethnic Chinese population was reported and only modest effects have been identified for variants of CD36 gene for metabolic syndrome, and the associations for metabolic syndrome itself have often been inconsistent." (PMID 23249574, 2012). "Since CD36 is known to associate with the metabolic syndrome and hyperlipidemia, CD36 variants may indirectly contribute to AMD via abnormal lipid metabolism." (PMID 22275803, 2012). "Therefore, we examined the association of common variants of the CD36 gene with the metabolic syndrome and components using a case–control study among ethnic Chinese adults, controlling for clinical and lifestyle factors." (PMID 23249574, 2012). "In addition, genetic variants of CD36 were related to acute myocardial infarction, type 2 diabetes, metabolic syndrome components, fatty acids and adiponectin levels, and free fatty acids." (PMID 23249574, 2012). "CD36 gene variants regulated fatty acid metabolism and accumulation of fat and fat metabolites, and may influence the risk of metabolic syndrome and may be a target for further personalized medicine screening." (PMID 23249574, 2012). "Moreover, CD36 polymorphisms have been associated with abnormal blood lipid levels, increased risk of coronary heart disease in diabetics, and increased risk of metabolic syndrome." (PMID 38674354, 2024). "Hence the conclusion that CD36 is associated with many components of the metabolic syndrome." (PMID 32796572, 2020). "To gain more insight into the contribution of CD36 rare coding mutations to T2D and its cardio-metabolic complications, we screened 184 unrelated French individuals of European ancestry presenting simultaneously with T2D, arterial hypertension, dyslipidemia and history of coronary heart disease." (PMID 31748580, 2019). "Importantly, decreased CD36 expression might be expected to modulate the dyslipidemia and attenuate the atherogenic risk in HIV patients." (PMID 30404938, 2018). "The CD36 gene may be a candidate susceptibility to dyslipidemia in Mexican population." (PMID 24188362, 2013).
metabolic syndrome (continued). "The elevated hepatic fatty acid transporter CD36 expression can result in dyslipidemia, thereby contributing to the NAFLD-related HCC progression." (PMID 40076869, 2025). "In contrast, the presence of Th17 cells confers protection against metabolic syndrome by decreasing intestinal lipid absorption, accompanied by the down-regulation of CD36 expression in the intestine." (PMID 40979562, 2025). "Special emphasis is on the signaling pathway induced by a platelet membrane protein, CD36, in dyslipidemia, and by protein disulfide isomerase (PDI), a member of the thiol oxidoreductase family of proteins." (PMID 38247507, 2024). "This is in line with findings demonstrating increased Cd36 expression in non-alcoholic fatty liver disease patients as well as contributing significantly to dyslipidemia in mice." (PMID 36209101, 2022). "In a clinical trial that involved patients with a metabolic syndrome, CD36 mRNA was downregulated in the blood mononuclear cells of patients who consumed a healthy low-fat diet." (PMID 33854480, 2021). "The purpose of this case-control study was to assess how haplotypes, genotypes and alleles distribution of the CD36 polymorphisms affects the prevalence of T2DM and dyslipidemia in the Jordanian population." (PMID 34648514, 2021). "After multivariate-adjustments by sex, dyslipidemia, previous CVD, psychotropics, statins, antiplatelet agents, and MNA > 23.5, total and AV+ CD141+/CD41+-CD61+, and PAC1+/AV+, CD141+/AV+, and CD36+/AV– cMV remained inversely associated with successful aging." (PMID 34395448, 2021). "An association between dyslipidemia, LDL oxidation, CD36 expression, ROS generation, thioredoxin-interacting protein (TXNIP) upregulation, and NLRP3 inflammasome activation was demonstrated by DSS exposure in HFD-fed rats." (PMID 33917884, 2021). "An association between dyslipidemia, the oxidation of LDL, CD36, ROS generation, TXNIP upregulation, NLRP3 inflammasome activation, and dysbiosis has been demonstrated in the present study through the action of DSS in HFD-fed rats." (PMID 33917884, 2021). "Conditions such as hyperglycemia and dyslipidemia significantly change CD36 expression, its function, and its signaling pathways." (PMID 32796572, 2020). "We sequenced coding regions of the cluster of differentiation 36 (CD36) gene in 184 French individuals of European ancestry presenting simultaneously with type 2 diabetes (T2D), arterial hypertension, dyslipidemia, and coronary heart disease." (PMID 31748580, 2019). "Cd36 upregulation induced by in vivo adenoviral delivery of the gene to the livers of mice was sufficient to increased hepatic triglyceride storage and dyslipidemia in mice." (PMID 30294300, 2018). "Although nonalcoholic steatohepatitis (NASH) is an important component of the metabolic syndrome, scavenger receptor CD36 also modulates NASH development." (PMID 30516003, 2018). "Our observations provide insight in the role of CD36 into the etiology of postprandial dyslipidemia." (PMID 26727015, 2016). "In this study, cardiac CD36 protein levels were increased in fructose-induced metabolic syndrome of rats, being consistent with elevation of serum ox-LDL levels under fructose induction." (PMID 27270216, 2016). "In support of this conclusion, it has been demonstrated that hepatic CD36 correlates with dyslipidemia in diet-induced obese animals; furthermore, overexpression of CD36 in the liver leads to increased fatty acid uptake and triglyceride storage in the liver." (PMID 27445980, 2016). "Cd36 is a fatty acid transport protein whose increased expression in the liver contributes to dyslipidemia before the onset of type 2 diabetes." (PMID 24959901, 2014). "The mechanism of the CD36 gene for the pathogenesis of metabolic syndrome components has been proposed as the following: First, in the CD36 knockout mice, defective uptake and utilization of long-chain fatty acids were found in muscle and adipose tissues." (PMID 23249574, 2012).
metabolic syndrome (continued). "Recently, a role for the CD36 scavenger receptor as well as for the ATP-binding cassette transporter A1 (ABCA1) in the genesis of HIV-related dyslipidemia has been propsed." (PMID 22558273, 2012). "Previous genetic studies showed various effects between CD36 locus and metabolic syndrome components." (PMID 23249574, 2012). "A coding variant that results in partial CD36 protein deficiency associated with higher HDL levels and was protective against the metabolic syndrome." (PMID 20360851, 2010). "A strong association has been observed between serum levels of HGF and the metabolic syndrome, although it is unclear if the molecular mechanism for this is related to the function of CD36." (PMID 16515687, 2006). "By promoting CD36-mediated uptake of lipid in ATMs, esculetin may exert benefits for maintaining postprandial homeostasis and postprandial dyslipidemia." (PMID 40365299, 2025). "The impacts of CD36 variants on EOCAD risk are mediated, at least partly, by dyslipidemia." (PMID 40040886, 2025). "Thus, oxLDL ligation to CD36 promotes platelet activation, generates procoagulant platelets, blunts inhibitory signaling, and contributes to a dyslipidemia-induced procoagulant state." (PMID 37239003, 2023). "CD36 uptakes LCFAs in tissues and promotes lipid accumulation and dyslipidemia." (PMID 36293149, 2022). "Instead of having a concerted effect, TSP1 could block the translocase fatty acid activity of CD36 in metabolic syndrome." (PMID 33854480, 2021). "CD36 genetic variants were also identified in humans characterized by high serum triglycerides, low HDL levels, and hyperglycemia with insulin resistance, all considered clinical features of metabolic syndrome." (PMID 29883404, 2018). "Emerging evidence indicating that variation in the CD36 gene may play a role in the pathogenesis of metabolic syndrome." (PMID 23249574, 2012). "Therefore anti-CD36 inhibitors were able to improve glucose tolerance in rodent animals with typical metabolic syndrome." (PMID 22662181, 2012). "Dyslipidemia evidenced in Cav-1-/- and CD36-/- mice is congruent once more with our hypothesis on involvement of Caveolin genes in the control of cholesterol homeostasis." (PMID 19134193, 2009). "Since dyslipidemia is one of the most critical risk factors for CAD and accounts for at least 50% of population-attributable risk, it is tempting to speculate that the increased EOCAD risk associated with CD36 variants may stem from atherogenic dyslipidemia." (PMID 40040886, 2025). "Therefore, rs1761667 may result in dyslipidemia by inhibiting the expression or function of the CD36 protein." (PMID 40040886, 2025). "Second, the metabolic syndrome itself, does not relate to the CD36 gene polymorphism in our study." (PMID 23249574, 2012). "Overall, the haplotype tagged SNPs of CD36 gene were not related to the risk of metabolic syndrome." (PMID 23249574, 2012). "Notably, a rapid loss of segmented filamentous bacteria occurs in adults with metabolic syndrome, and colonization with segmented filamentous bacteria specifically decreases intestinal lipid uptake and absorption by controlling the epithelial expression of CD36." (PMID 40979562, 2025). "In the case of the adipocytes derived from subADMSCs, the plasmalemmal expression of CD36/SR-B2 seemed to be affected by both AS160 silencing (35% of data variability, p < 0.01) and metabolic syndrome (38% of data variability, p < 0.01)." (PMID 37602323, 2023). "Towards further understanding of the role of CD36 protein and gene in T2DM and dyslipidemia, a protein-protein interaction network and meta-analysis were carried out." (PMID 34648514, 2021). "Different studies on CD36 have shown that this receptor plays a key role in a number of disorders such as CVD, hypertension, and metabolic syndrome." (PMID 31185924, 2019). "Many studies have been conducted on CD36 rs1761667 in CVD, T2DM, metabolic syndrome and obese groups." (PMID 31185924, 2019).
metabolic syndrome (continued). "Many genes such as APOB, LPL, APOA1, LEP, CD36, IL-6, and APOE may play an important role in dyslipidemia." (PMID 36061816, 2022). "Recent research has established that apigenin is a PPAR modulator that inhibits obesity-induced metabolic syndrome via suppressing PPARγ and PPARα, resulting in activation/inhibition of upstream or downstream targets, such as STAT3, C/EBP-α, SREBP-1c, CD36, and Nrf2 in adipose tissues." (PMID 36092543, 2022). "The interaction of CD36 with TSP1 may also regulate the damage induced by saturated FFAs during obesity and dyslipidemia." (PMID 33854480, 2021). "CD36 is an important target for treating NAFLD and metabolic syndrome." (PMID 30037134, 2018). "Therefore, the attenuation of oxidative stress and ROS to suppress CD36-mediated TLR4/6-IRAK4/1 signaling and NLRP3 inflammasome activation by cinnamaldehyde and allopurinol may be a promising therapeutic strategy for the treatment of metabolic syndrome-associated heart disease." (PMID 27270216, 2016). "In keeping with the absence of the metabolic syndrome features, soluble CD36 levels are significantly lower in the HNF1A-MODY participants when compared to the normoglycaemic HNF1A-MODY negative family control group and the T2DM group." (PMID 24069322, 2013). "The investigation of SNP of CD36 on HDL is not well established, likely because participants in many studies deal with chronic diseases, including DM, CHD, or metabolic syndrome or risk factors for chronic diseases." (PMID 23656756, 2013). "In this table, the outcome (Yes or No) reveals whether or not there is an association between CD36 rs1761667 and rs1527483 polymorphisms and T2DM or metabolic syndrome." (PMID 34648514, 2021).